ADAM10 (ADAM metallopeptidase domain 10)
Diseases named in the same sentence as ADAM10 in open-access papers (continued):
Sharing a sentence is not in itself a finding about the gene and the disease.
gastric adenocarcinoma (3 papers, 2016 to 2022). "Here, we investigated the association of ADAM10 expression with prognosis in gastric adenocarcinoma patients that underwent gastric resection with D2 lymph node dissection." (PMID 33679947, 2021). "The aim of this study was to investigate the association of ADAM10 expression with prognosis and histopathological prognostic markers in patients with gastric adenocarcinoma that underwent gastric resection with D2 lymph node dissection." (PMID 33679947, 2021). "For example, ADAM-10 was up-regulated in AFP producing gastric adenocarcinoma tumor tissues with poor histology grade and distal location, while DPYD was down-regulated in the tumor tissues with moderate histology grade and without vascular invasion." (PMID 27057629, 2016). "Immunohistochemical ADAM10 expression may be used as a prognostic marker in gastric adenocarcinoma, however, introduction of a standardized immunohistochemical scoring system seems to be necessary for evaluation of ADAM10 staining." (PMID 33679947, 2021). "One available study showed high levels of ADAM10 and ADAM17 transcripts in gastric adenocarcinoma." (PMID 36286024, 2022).
heart failure (3 papers, 2021 to 2026). Inability of the heart to pump blood at an adequate rate to meet tissue metabolic requirements. "We demonstrate that inhibition of the sheddase ADAM10 early after MI by either a pharmacological inhibitor or genetic ablation improves survival and cardiac function and alleviates progression to severe heart failure." (PMID 36496449, 2022). "Moreover, ADAM10 expression correlates well with two commonly measured fetal genes and markers of heart failure, NPPA and NPPB29." (PMID 36496449, 2022). "The ADAM10-dependent shedding of N-cadherin may regulate cardiac remodeling in DCM, which provides new insights for the management of DCM and heart failure." (PMID 34522779, 2021).
Hypertension (3 papers, 2015 to 2025). The presence of chronic increased pressure in the systemic arterial system. "Certainly, the expression of ADAM10 in mice of the Pb + hypertension group rose from 2 w until peaking at 8 w in the PFC and hypothalamus, at 4 w exposure in the hippocampus; then, they returned to the control level after 12 w exposure." (PMID 39853035, 2025). "ADAM10 protein expression in mice of the hypertension group or Pb group showed the upper in the hippocampus at 2 w exposure and in the PFC and hypothalamus at 4 w and 8 w exposure, respectively, peaking at 4 w or 8 w exposure." (PMID 39853035, 2025). "Next, to further elucidate whether ADAM10 or ADAM17 were mainly involved in the proteolytic shedding of TREM2 following hypertension and Pb exposure, we examined the protein expressions of ADAM10 and ADAM17 in vivo." (PMID 39853035, 2025). "ADAM10 or ADAM17, the enzymes cleaving TREM2, were detected to elucidate the mechanism of TREM2 decrease in mice with hypertension, Pb alone, or co-exposure." (PMID 39853035, 2025).
hypopharyngeal squamous cell carcinoma (3 papers, 2019 to 2021). "In hypopharyngeal squamous cell carcinoma, expression of miR-140-5p suppressed cancer cell migration and invasion abilities by regulating ADAM10-mediated Notch1 signaling." (PMID 34884487, 2021). "MiR-140-5p was down-regulated in hypopharyngeal squamous cell carcinoma (HSCC) tissues and cell lines and restoration of miR-140-5p in HSCC cells repressed tumor cell invasion and migration via targeting ADAM10/Notch1 axis." (PMID 31762692, 2019).
lung adenocarcinoma (3 papers, 2022 to 2025). A carcinoma that arises from the lung and is characterized by the presence of malignant glandular epithelial cells. "The migratory and invasive capabilities of lung adenocarcinomas and squamous cell carcinomas are governed by ADAM10." (PMID 39512767, 2024). "IT was found that miR-140-3p is the miRNA that acts on ADAM10, miR-140-3p can inhibit the activity of the Notch pathway by acting on ADAM10, and ultimately up-regulates the sensitivity of lung adenocarcinoma cells to anti-tumor drugs." (PMID 36606198, 2022). "Our study focused on the expression level of ADAM17 and ADAM10 in lung adenocarcinoma related specimens and the expression level of miRNA acting on ADAM10, and finally found that miR-140-3p in lung adenocarcinoma tissues has more clinical significance compared with other miRNAs." (PMID 36606198, 2022). "Recently, by collecting protein mass spectrometry data from 74 stage I lung adenocarcinoma (LUAD) patients from Taiwan, Lu and colleagues 13 revealed five prognostic biomarkers, ADAM10, MAOA, MIF, TEK, and THBS2." (PMID 39991567, 2025). "In this study, the expression of two ADAMs in lung adenocarcinoma (LUAD) tissues was first determined, and it was found that ADAM10 is the main ADAM subtype that plays a major role in LUAD." (PMID 36606198, 2022).
malignant glioma (3 papers, 2024 to 2025). A grade III or grade IV glioma arising from the central nervous system. "Additionally, the neuron-specific protein neuroligin-3 (NLGN3), once cleaved by a disintegrin and metalloproteinase domain-containing protein 10 (ADAM10), drives malignant glioma proliferation." (PMID 41163091, 2025).
mantle cell lymphoma (3 papers, 2012 to 2021). Mantle cell lymphoma is a rare form of malignant non-Hodgkin lymphoma affecting B lymphocytes in the lymph nodes in a region called the ``mantle zone''. "Constitutive activation of ADAM10 contributes to the growth of mantle cell lymphoma (MCL) cells." (PMID 33413403, 2021). "This may be ADAM10: ADAM10 has shown TNF-α sheddase activity in ADAM17-deficient murine fibroblasts and has been implicated in TNF-α production in mantle cell lymphoma." (PMID 22792380, 2012). "Knockdown of ADAM10 using siRNA in mantle cell lymphoma cells induces cell-cycle arrest but not apoptosis." (PMID 33413403, 2021).
memory impairment (3 papers, 2022 to 2024). "This study was designed to determine the potential of apicidin treatment to reverse learning and memory impairments in an AD mouse model and the possible correlation of these effects with ADAM10." (PMID 36708130, 2023). "We found that the oral B. breve MCC1 274 supplementation prevented memory impairment in AppNL-G-F mice and decreased hippocampal Aβ levels through the enhancement of the a-disintegrin and metalloproteinase 10 (ADAM10) level." (PMID 34958017, 2022). "Therefore, we investigated the potential of apicidin treatment to reverse learning and memory impairments in an AD mouse model and the possible correlation of these effects with ADAM10." (PMID 36708130, 2023). "Altogether, the present study provides evidence that apicidin treatment ameliorated memory impairment in APP/PS1 mice, and this effect was attributed to decreasing the Aβ burden by promoting the expression of ADAM10." (PMID 36708130, 2023).
mesothelioma (3 papers, 2016 to 2024). A usually malignant and aggressive neoplasm of the mesothelium which is often associated with exposure to asbestos. "We also demonstrate that ADAM10 sheddase downregulation decreases the production of a soluble N-cadherin fragment through membrane N-cadherin, which stimulated mesothelioma cell migration." (PMID 30651596, 2019). "As N-cadherin is a substrate of ADAM10 and given its putative role in cell migration, we investigated a potential relationship between ADAM10 and N-cadherin in our model of mesothelioma cell migration." (PMID 30651596, 2019). "In order to examine the potential implication of ADAM10 in mesothelioma tumour progression, AB12 and PM27 were transduced with an ADAM10 shRNA lentiviral vector, which, as expected, strongly decreased ADAM10 production." (PMID 30651596, 2019). "Strikingly, ADAM10 remained overexpressed in mesothelioma tumours induced by the in vivo injection of AB12 or PM27 cells as compared to CPL isolated from diaphragms of healthy mice." (PMID 30651596, 2019). "In the present study, ADAM10 overexpression in mesothelioma is supported by both in vitro and in vivo results, in particular in tissues derived from age-matched mice." (PMID 30651596, 2019). "In this study, we provide for the first time evidence that ADAM10 is overexpressed in human MPM samples and, by using experimental mouse models of mesothelioma development, we demonstrate the link between ADAM10 and MPM progression." (PMID 30651596, 2019). "Notably, ADAM metallopeptidase domain 10 (Adam10) and inhibin subunit beta A (Inhba) were also upregulated, and their upregulation was predicted to lead to the activation of mesothelioma formation." (PMID 38297314, 2024). "Moreover, ADAM10 downregulation in murine mesothelioma cells significantly impairs MPM progression in vivo after intrapleural cell injection." (PMID 30651596, 2019). "This signalling cascade induced by ADAM10 protease could also be targeted in mesothelioma as development of selective FGFR inhibitors for clinical trials is in progress." (PMID 30651596, 2019). "ADAM10 inhibition is worth considering as a therapeutic perspective in mesothelioma context." (PMID 30651596, 2019). "In addition, we report that the inhibition of the ADAM10-dependant generation of a soluble N-cadherin ectodomain fragment leads to reduced mesothelioma cell migration." (PMID 30651596, 2019). "Biological functions of ADAM10 in MPM were investigated by inhibition studies using shRNA and an ADAM10 pharmacological inhibitor (GI254023X) in AB12 and PM27 mesothelioma cells as well as in H28 cells by using siADAM10." (PMID 30651596, 2019). "Taken together, we demonstrate that ADAM10 is overexpressed in MPM and takes part to MPM progression through the generation of N-cadherin fragment that stimulates mesothelioma cell migration." (PMID 30651596, 2019). "Distribution of the different phases of the cell cycle was also not affected in mouse cells indicating that ADAM10 is not a major regulator of cell proliferation in mesothelioma progression." (PMID 30651596, 2019). "We show, in vitro, that ADAM10 targeting through shRNA and pharmacological (GI254023X) approaches reduced drastically mesothelioma cell migration and invasion, as well as for human mesothelioma cells treated with siRNA targeting ADAM10." (PMID 30651596, 2019). "ADAM10 silencing in mesothelioma H28 cells using siRNA did not modify proliferation rates as compared to siScramble-treated cells except a slight difference at 24 h." (PMID 30651596, 2019). "Analysis of ADAM10 expression in mesothelioma PM27 cells and in commercial mesothelioma AB12 cells revealed increased ADAM10 protein production as compared to non-malignant mesothelial cells." (PMID 30651596, 2019). "In addition, invasion capacities of mesothelioma AB12 and PM27 cells from spheroids in a 3D-collagen gel were significantly decreased when ADAM10 expression was inhibited." (PMID 30651596, 2019).
mesothelioma (continued). "Interestingly, ADAM10 expression analysis revealed increased ADAM10 protein production in mesothelioma H28 cells as compared to non-malignant mesothelial Met5A cells." (PMID 30651596, 2019). "In MPM, we showed that mesothelioma cell (AB12, PM27 and H28) proliferation is not modified when ADAM10 is targeted with shADAM10, GI254023X or siADAM10." (PMID 30651596, 2019).
oral squamous cell carcinoma (3 papers, 2020 to 2025). "Odds ratio and 95% confidence intervals of clinical statuses associated with genotypic frequencies of ADAM‐10 rs383902 in male oral squamous cell carcinoma patients." (PMID 36946281, 2023). "Odds ratio and 95% confidence intervals of clinical statuses associated with genotypic frequencies of ADAM‐10 rs653765 in male oral squamous cell carcinoma patients." (PMID 36946281, 2023). "A disintegrin and metalloproteinase domain‐containing protein 10 (ADAM‐10) involves in the tumour progression, but the impacts of single‐nucleotide polymorphism (SNP) of ADAM‐10 on oral squamous cell carcinoma (OSCC) remain unclear." (PMID 36946281, 2023).
preeclampsia (3 papers, 2018 to 2022). Preeclampsia is a hypertensive disorder of pregnancy that is characterized by new-onset hypertension with proteinuria presenting after 20 weeks of gestation, and depending on mild or severe forms may initially present with severe headache, visual disturbances, and hyperreflexia. "ADAM10 has also been shown to mediate the release of the soluble Flt-1 isoform, a known marker of preeclampsia and knockdown of ADAM10 leads to decreased sFlt-1." (PMID 35562897, 2022). "ADAM10 has previously been observed to increase in pre-term preeclampsia, and through its action in protein secretion may contribute to increased placental shedding of soluble fms-like tyrosine kinase 1 (sFlt1); a factor thought to play an important role in preeclampsia pathogenies." (PMID 30455461, 2018).
renal fibrosis (3 papers, 2018 to 2025). A final common manifestation of a wide variety of chronic kidney diseases characterized by glomerulosclerosis and tubulointerstitial fibrosis. "Notch signaling is activated through ADAM10-mediated proteolytic reactions, and the ADAM10-Notch signaling axis is associated with renal fibrosis." (PMID 40822939, 2025). "To investigate the role of ADAM10 in renal fibrosis in vivo, we assessed the renal expression of ADAM10 in a rat model of UUO." (PMID 30117015, 2018). "Our results, for the first time, indicate that PAX2 promotes EMT in the renal tubular epithelia via directly activating ADAM10, and that ADAM10 participates in the pathogenesis of renal fibrosis." (PMID 30117015, 2018). "As we observed ADAM10 to be activated in a rat renal fibrosis model, we next assessed ADAM10 expression in renal biopsy tissues from five CKD patients (stages 2–3) with tubulointerstitial injury and 1 without CKD." (PMID 30117015, 2018). "In the current study, we investigated the influence of ADAM10 on PAX2-induced EMT in renal tubular epithelia and the effect of ADAM10 in renal fibrosis." (PMID 30117015, 2018). "Another important substrate of ADAM10 is the Notch receptor and ligand, Delta, which also plays a crucial role in renal fibrosis." (PMID 30117015, 2018). "In summary, our findings shed light on the mechanism of PAX2-induced EMT and renal fibrosis and the up-regulation of ADAM10." (PMID 30117015, 2018). "Finally, ADAM10 was up-regulated in the obstructive kidneys in a time-dependent manner and correlated with renal fibrosis in vivo." (PMID 30117015, 2018). "The contribution of ADAM10 over-expression to PAX2-induced EMT deepens our understanding of renal fibrosis and may inform development of anti-fibrogenic strategies." (PMID 30117015, 2018). "However, whether ADAM10 activates the Notch signaling pathway in renal fibrosis requires further investigation." (PMID 30117015, 2018). "As PAX2 was observed to induce EMT in renal tubular epithelial cells, and PAX2 could regulate ADAM10 in several cell types, we hypothesized that PAX2 may regulate ADAM10 activity in the renal tubular epithelia, and that ADAM10 might be implicated in the pathogenesis of EMT and renal fibrosis." (PMID 30117015, 2018). "PAX2 directly increased expression of ADAM10, the presence of which contributed to EMT in renal tubular epithelia and hence plays an important role in renal fibrosis." (PMID 30117015, 2018). "However, the regulation and function of ADAM10 in renal fibrosis still remains unclear." (PMID 30117015, 2018). "In this sense, our data provide the first clear in vitro and in vivo evidence that ADAM10 is involved in EMT of renal tubular epithelial cells and in renal fibrosis." (PMID 30117015, 2018). "This study provides evidence that ADAM10 is involved in the EMT of renal tubular epithelia and renal fibrosis." (PMID 30117015, 2018).
retinoblastoma (3 papers, 2021 to 2022). A malignant tumor that originates in the nuclear layer of the retina. "A previous study by our group revealed significantly increased ADAM10 and ADAM17 protein and RNA expression levels in retinoblastoma cell lines, as well as upregulated RNA levels in RB patient tumor samples as compared to the healthy human retina." (PMID 36293469, 2022). "Testing for changes in anchorage-independent growth, soft agarose assays revealed that ADAM10 and ADAM17 depleted Y79, and WERI-Rb1 retinoblastoma cells displayed a significantly reduced colony formation capacity." (PMID 36293469, 2022). "These correlation patterns suggest that at least miR-145 is a potential regulator of ADAM10 and ADAM17 in retinoblastoma." (PMID 36293469, 2022). "Thus, the significance of ADAM10 and ADAM17 for tumor growth, tumor cell migration, invasion, and metastasis seems to be cell type dependent, and our data suggest that ADAM17 plays a pivotal role in retinoblastoma development." (PMID 36293469, 2022). "The study presented focuses on the involvement of ADAM10 and ADAM17 in retinoblastoma (RB), the most common malignant intraocular childhood tumor." (PMID 36293469, 2022).
temporal lobe epilepsy (3 papers, 2016 to 2020). A localization-related (focal) form of epilepsy characterized by recurrent seizures that arise from foci within the temporal lobe, most commonly from its mesial aspect. "Our findings suggest that miR-23a targeting of ADAM10 contributes to epileptogenesis in temporal lobe epilepsy." (PMID 31114485, 2019).
tongue squamous cell carcinoma (3 papers, 2015 to 2024). A squamous cell carcinoma that arises from the tongue. "In the present study, the effect of ADAM10 gene silencing on the proliferation, migration and invasion of the human tongue squamous cell carcinoma cell line TCA8113 was investigated." (PMID 25333745, 2015). "The present study aimed to investigate the effect of A disintegrin and metalloproteinase 10 (ADAM10) gene silencing on the proliferation, migration and invasion of the human tongue squamous cell carcinoma cell line TCA8113." (PMID 25333745, 2015). "Besides, the silencing of ADAM‐10 can influence the invasion, migration and proliferation of specific human tongue squamous cell carcinoma cell line, and the up‐regulation of ADAM‐10 was observed in patients with OSCC." (PMID 36946281, 2023).
uveal melanoma (3 papers, 2020 to 2025). A melanoma derived from melanocytes of the uveal tract. "In uveal melanomas, miR144 was shown to act as tumor suppressor miRNA through ADAM10 and c-Met modulation." (PMID 37387784, 2023).
acute leukemia (2 papers, 2023 to 2025). A clonal (malignant) hematopoietic disorder with an acute onset, affecting the bone marrow and the peripheral blood. "Our findings align with recent studies highlighting the critical role of ADAM10 in acute leukemia and its potential as a therapeutic target." (PMID 40746920, 2025). "A disintegrin and metalloproteinase domain-containing protein 10 (ADAM10) was identified as an essential vulnerability required for the survival and growth of different types of acute leukemias in vivo, and reconstitution assays in PDX models confirmed the relevance of its sheddase activity." (PMID 37422628, 2023). "We identified ADAM10 as essential for acute leukemias in vivo." (PMID 37422628, 2023). "In conclusion, ADAM10 might represent a novel therapeutic target to treat acute leukemias, both ALL and AML." (PMID 37422628, 2023). "Although ADAM10 has been shown to be upregulated in a subset of hematologic malignancies and to drive T-ALL through oncogenic NOTCH1 signaling, its functional role in most subtypes of acute leukemia remains elusive." (PMID 37422628, 2023). "Overall, dependency on ADAM10 was demonstrated in seven out of eight AL PDX models in vivo, suggesting that ADAM10 plays an essential role in both types of acute leukemia, ALL and AML, independent of the molecular subtype or genetic abnormalities." (PMID 37422628, 2023).